RAC1 (Rac family small GTPase 1)
Diseases named in the same sentence as RAC1 in open-access papers (continued):
Sharing a sentence is not in itself a finding about the gene and the disease.
cancer (continued). "We experimentally tested the activating potential of rare mutations identified in 3D clusters in the MAP2K1 and RAC1 proteins, enlarging the number of biologically and potentially clinically significant alleles in these two critical effectors of activated signaling pathways in cancer." (PMID 28115009, 2017). "Similarly to other Rho GTPases, Rac1 is also implicated in cell cycle progression, gene transcription and the release of pro-angiogenic factors and subsequent promotion of neovascularization, thereby promoting cancer initiation, progression and metastasis." (PMID 27442895, 2017). "On the contrary, the effect could be reversed with inhibition of the cytosolic O2− scavenger Cu/ZnSOD, thus indicating that the apoptotic resistance of oncogenic Ras-expressing cancer cells could be associated with an increase in steady-state intracellular O2− mediated through Rac1 activation." (PMID 23316476, 2012). "Subsequent functional annotation analysis revealed that the DEGs were enriched for cancer‐ and RAC1‐related pathways, including epithelial cell proliferation, cell projection organization, and GTPase activity." (PMID 40548642, 2025). "Exosome‐derived miRNAs have been shown to effectively block cancer cell proliferation, and exosomes derived from TAMs contain miR‐142‐3p, which inhibits tumour growth and action by targeting RAC1." (PMID 40717227, 2025). "Specifically, RAC1 is negatively correlated with all three B cell subsets—naïve B cells, memory B cells, and plasma cells—in cancers such as BLCA, BRCA, CESC, KIRC, LAML, LGG, STAD, and STES." (PMID 39898257, 2025). "The analysis revealed that a significant proportion of the cells expressed either RhoA, Rac1, or both, indicating the presence of these proteins across most of the cancer cell population." (PMID 39887960, 2025). "We developed a prognostic signature combining RAC1 expression and B cell infiltration, which effectively predicts prognosis across cancer types." (PMID 39898257, 2025). "RAC1 demonstrated strong predictive capacity across 28 types of cancers, with AUC values ranging from 0.695 to 1.00." (PMID 39898257, 2025). "Although the role of RhoA and Rac1 in cancer progression is well‐established, it is interesting to further investigate how mechanical strain influences their expression and activity in CRC." (PMID 39887960, 2025). "Rac1 has been considered a central signaling hub essential for many oncogene-induced transformations, playing a crucial role in cancer cell proliferation, migration, and invasion." (PMID 40948788, 2025). "This study conducted a comprehensive analysis of the expression patterns of RAC1 at the pan-cancer level and its relationship with cancer progression, prognosis, immune microenvironment." (PMID 39898257, 2025). "Yet, based on TCGA Pan-Cancer Atlas data, RAC1 gene copy increases (amplification/gain) are found in 37% of pan-cancer cases (n = 10,967)." (PMID 39941730, 2025). "The subsequent assessment of RhoA and Rac1 expression across the cancer cell population revealed that these biomarkers are widely present, with a significant portion of cells expressing one or both proteins." (PMID 39887960, 2025). "Background/Objectives: Rho-GTPase signaling is involved in cancer progression and chemoresistance, with Ras-related C3 botulinum toxin substrate 1 (Rac1) being a major regulator." (PMID 39941828, 2025). "To explore RAC1 expression in primary cancers versus adjacent normal tissues, we analyzed RNA sequencing data from TCGA and GTEx." (PMID 39898257, 2025). "Integrin localization in LRs has a clear meaning in the cancer context, as it directs the localization and local activity of potent drivers of tumor progression, such as the small GTPase Rac1." (PMID 39900574, 2025). "This study comprehensively analyzed RAC1 expression across various cancers, revealing significant upregulation in many cancer types." (PMID 39898257, 2025).
cancer (continued). "In some cases, the interaction between NaV1.5 and Rac1 can enhance cancer cell migration and invasion by activating the PI3K/AKT pathway." (PMID 39673684, 2025). "ISG15 is also involved in cancer cell migration by binding to and activating the Rho GTPase family member Rac1, and regulating traditional EMT (epithelial–mesenchymal transition) signaling among others." (PMID 40208307, 2025). "The interaction between NaV1.5 and Rac1 also involves various small molecules and proteins, which play crucial roles in regulating cell migration, invasion, and other cancer-related processes." (PMID 39673684, 2025). "Pak3 is a well-known downstream effector of Cdc42 and Rac1 GTPases that mediates motility and MAPK activation associated with cancer invasion and metastasis." (PMID 40348815, 2025). "SOX1 suppresses Rac1 activity, a key member of the Rho family of GTPases that regulates actin cytoskeletal remodeling and membrane protrusion formation—critical steps in cancer cell motility." (PMID 40699796, 2025). "This study investigates the expression patterns of RhoA and Rac1 under mechanical strain in post‐surgical CRC clinical samples to elucidate their roles in cancer progression and identify therapeutic targets." (PMID 39887960, 2025). "Our findings offer novel mechanistic and clinical insights into the roles of RAC1 and splicing dysregulation in cancer." (PMID 40548642, 2025). "To determine if somatic RAC1 gene copy number would likely govern RAC1 mRNA expression in pan-cancers including HNSCC tumors, we examined the correlation between RAC1 gene copy number and its intra-tumoral mRNA expression level using bulk RNA-seq data." (PMID 39941730, 2025). "The upregulation of RhoA and Rac1 in response to mechanical stress highlights the critical role of the tumor microenvironment in cancer progression." (PMID 39887960, 2025). "IMPDH has been shown to enhance cancer cell growth and invasion through direct interaction with certain proteins, such as B7‐H3, YB‐1 and RAC1." (PMID 40186514, 2025). "KS is the most frequent cancer associated with AIDS, and in our mouse model, was induced by overexpression of a constitutively activated Rac1 (Rac1V12) using the smooth muscle cell actin promoter for expression (likely resulting in RacV12 pericytes)." (PMID 40328105, 2025). "Overexpression or activation of some RAC GEFs such as VAV, TIAM, or DOCK is also responsible for upregulation of RAC1 signaling in cancers." (PMID 40633540, 2025). "An incresaing number of studies have gradually highlighted the pivotal role of RhoA and Rac1 in cancer development and progression." (PMID 39887960, 2025). "This single-cell analysis, spanning 14 types of cancers, revealed that RAC1 is expressed in a variety of cell subpopulations, including CD8 T cells, dendritic cells (DC), endothelial cells, and fibroblasts." (PMID 39898257, 2025). "Lastly, Paxillin phosphorylation at S83 was detected, a site previously linked to Rac1 activation and cytoskeletal remodeling via ERK signaling, processes already observed in our experiments and that are important for cancer metastases." (PMID 40629272, 2025). "Based on RAC1 expression and B cell interaction, a prognostic signature was established to predict prognosis at the pan-cancer level." (PMID 39898257, 2025). "This consistent upregulation of both RhoA and Rac1 in more advanced tumors points to their potential as key biomarkers for cancer progression." (PMID 39887960, 2025). "This pathway ultimately affects cancer cell proliferation through cyclins and p21, and cell migration through the small GTPase Rac-1 and f-actin organization." (PMID 39900574, 2025). "We finally aimed to study the genes implicated in cancer cell migration as a mechanism of rescue, thus we analyzed the expression of ACTN1, PTGS2, and RAC1." (PMID 40032892, 2025).
cancer (continued). "The misregulation of RAC1 in cancer is also frequently related to the deregulation of molecular mechanisms involved in the control of RAC1 activity, degradation, or localization." (PMID 40633540, 2025). "The mechanism of Rac1 signaling in cancer is usually the result of an increase in upstream inputs from tyrosine kinase receptors (PI3Ks) or GEFs (such as VAV, Prex and TIAM) or a decrease inRac1 inactivation caused by GAP." (PMID 39673684, 2025). "In alignment with previous findings, our study also detected significant levels of Rac1 in clinical cancer samples and cancer cells compared to non‐cancer cells." (PMID 39887960, 2025). "In particular, some of the guanine nucleotide exchange factors (GEFs) that activate RAC1 by exchanging GDP for GTP, such as TIAM1, ECT2, PREX, and VAV family members, have been found to be overexpressed or mutated in cancer." (PMID 40633540, 2025). "The diverse signaling activities of RAC1 in human cells and cancers are primarily mediated through its interactions with downstream effectors." (PMID 41034404, 2025). "We, the authors, have a patent application related to this work: Patent WO2018224563: Inhibitors of RAC1 and uses thereof for treating cancers." (PMID 40633540, 2025). "Overall, the prognostic model based on RAC1 and B cell infiltration demonstrates significant prognostic value at the pan-cancer level, indicating that patients with a high RPBI score have poorer prognosis." (PMID 39898257, 2025). "Rho-GTPase signaling, which includes Ras-related C3 botulinum toxin substrate 1 (Rac1) as a major regulator, is involved in cancer progression and chemoresistance; however, the role of Rac1 in MM remains elusive." (PMID 39941828, 2025). "We explored the role of RAC1 in forming CICs between SDCSCs and parental cancer cells through a RAC1-GTP pull-down assay." (PMID 40225568, 2025). "Previous studies identified RAC1 as a key player in various aspects of carcinogenesis and metastasis, and we confirmed that high levels of RAC1 mRNA expression in cancer tissues from the Cancer Genome Atlas correlated with a high mortality rate." (PMID 40633540, 2025). "This research focuses on two crucial players: RhoA and Rac1, small yet powerful proteins that regulate the structure and movement of cancer cells." (PMID 39887960, 2025). "The results revealed a broad distribution of RAC1 expression in cancers characterized by either elevated or reduced TMB and MSI." (PMID 39898257, 2025). "PREX1 ranked among the most significantly more accessible genes in older adults, coding for the guanine-nucleotide exchange factor (GEF) for RAC1, which is known to function in cancer cell proliferation and metastasis." (PMID 38329813, 2024). "AXL was shown to interact with several proteins contributing to cancer cell migration and invasion via RAC1 activation." (PMID 39527598, 2024). "RAC1 is not only involved in the tumor cell cycle, proliferation, migration, invasion, and angiogenesis but is also involved in the regulation of cancer stem cells and immune evasion mediated by tumor microenvironment." (PMID 38378644, 2024). "The activation of Rac1 has been demonstrated to facilitate the progression of cancer, potentially leading to an increase in exosome biogenesis." (PMID 39062561, 2024). "In conjunction, TAZ confers stem cell-like properties in cancer cells following VEGF/Nrp2-mediated activation of Rac1." (PMID 38592275, 2024). "We recently identified a ΔNp63α/miR-320a/PKCγ signaling axis that regulates cancer cell invasion by inhibiting phosphorylation of the small GTPase Rac1, a master switch of cell motility that positively regulates cell invasion in multiple human cancers." (PMID 38191532, 2024). "The expression and activation of Rac1 are commonly increased in diverse cancer types, including breast cancer, colon cancer, and lung cancer." (PMID 38344200, 2024).
cancer (continued). "NET-DNA can bind to coiled-coil domain containing protein 25 (CCDC25) on cancer cells, activating the integrin-linked kinase (ILK)-β-parvin-ras-related C3 botulinum toxin substrate 1 (RAC1)-cell division control protein 42 (CDC42) cascade within cancer cells." (PMID 39143953, 2024). "Our data suggest that RAC1 expression is upregulated in PTX‐resistant cancer cells, thereby promoting signaling via the PAK4/MAPK pathway and inhibiting chemotherapy‐induced pyroptosis." (PMID 39224538, 2024). "In conclusion, these studies in both RAB4A-high and RAB4A-low cancer cells demonstrate that RAC1 is upstream of SOX2 in the RAB4A regulation of cancer stemness, while the order of regulation among RAC1, NUMB, and NOTCH1 are yet to be defined." (PMID 39463384, 2024). "Our data provide critical insight into the nature of ΔNp63α effectors and underscore a novel regulatory signaling pathway for Rac1-mediated cancer cell invasion." (PMID 38191532, 2024). "We postulate that ΔNp63α is a promising therapeutic target for reducing the Rac-GEF/Rac1 metastatic signaling in cancer." (PMID 38191532, 2024). "In recent decades, research has presented compelling evidence regarding the pivotal involvement of Rac1 in the advancement and proliferation of cancer cells." (PMID 38344200, 2024). "PAK1 is a key downstream effector of the small GTPase Rac1, which plays important roles in cancer cell migration and invasion." (PMID 38227562, 2024). "The transmembrane protein CCDC25 functions as a receptor for NETs-DNA on the surface of cancer cells, activating the ILK/β-parvin/RAC1 pathway and enhancing cancer cell motility by sensing extracellular NETs-DNA." (PMID 38664728, 2024). "(ii) CGN c.3560C > T induces the overexpression of IQGAP1 and activates Rac1 in cancer cells, providing molecular insights into the mechanisms by which this variant influences cellular behavior." (PMID 38424547, 2024). "Due to its significant involvement in oncogenesis and the advancement of cancer, Rac1 has garnered attention as a promising target for therapeutic intervention in cancer management." (PMID 38344200, 2024). "For instance, 14-3-3 binds directly to RhoGDI1 phosphorylated at Ser174, releasing RhoA, Rac1, and Cdc42, promoting Rho GTPases activation and resulting in increased cancer cell invasion and metastasis." (PMID 39768163, 2024). "The current research explores the surprising application prospects of RAC1 inhibitors in cancer prevention and treatment, especially in HCC." (PMID 38378644, 2024). "Our results elucidated a novel molecular mechanism by which ΔNp63α negatively affects cancer cell invasion and identifies the ΔNp63α/Rac1 axis as a potential target for metastasis." (PMID 38191532, 2024). "It will be interesting to identify in future studies other RAC1 downstream effectors that transmit signals for cancer stemness regulation." (PMID 39463384, 2024). "Here, VEGF/Nrp2 signaling contributes to PD-L1 expression on cancer cells through the activation of the guanosine triphosphatase (GTPase) Rac1 and the transcriptional coactivators YAP/TAZ." (PMID 38592275, 2024). "We also employed an immunofluorescent assay to assess the expression levels of GTP-bound Rac1 in cancer cells." (PMID 38424547, 2024). "Protein extraction from the cell membrane of cancer cells before and after hypoxia revealed that the RAC1 content increased in the cell membrane after hypoxia." (PMID 38378644, 2024). "So far, we have demonstrated that NUMB, NOTCH1, and RAC1 regulate cancer cell self-renewal downstream of RAB4A, and that this signaling chain controls the transcription of SOX2." (PMID 39463384, 2024). "Our investigation has revealed a notable association between the CGN c.3560C > T genotype, Rac1 activation, and the EMT program in cancer cells." (PMID 38424547, 2024). "We recently showed that ΔNp63α reduces Rac1 signaling by inhibiting protein kinase C γ (PKCγ), which in turn inhibits cancer cell invasion." (PMID 38191532, 2024).
cancer (continued). "This phosphorylation event facilitated cancer cell proliferation and motility by activating RhoA and Rac1." (PMID 39768163, 2024). "In cancer cells, Rac1 activity is suppressed at the cell equator during metaphase and anaphase to promote RhoA-dependent restriction of actomyosin contractility to a narrow zone for efficient membrane ingression in early cytokinesis." (PMID 38324689, 2024). "RAC1 is an important cancer driver downstream of KRAS and its ablation in mouse models delayed the onset of precancerous lesions and led to an inability to sustain precancer progression to PDAC." (PMID 38712822, 2024). "Aplidin activates p27Kip1, which is upstream and negatively regulates the activity of the cell cycle inhibitors RAC1/2; RAC1 inhibitors are emerging as an interesting bullet to treat various forms of cancer." (PMID 39062946, 2024). "The mechanisms leading to elevated Rac1 activity in cancer are not fully understood, and to date, efforts to exploit Rac1as a therapeutic target in cancer have not been comprehensively examined." (PMID 38191532, 2024). "Recent reports also linked high C1GALT1 expression to poor prognosis and the promotion of cancer cell proliferation, migration, and invasion through the regulation of RAC1 in LUAD." (PMID 38662050, 2024). "We further delved into the regulatory relationship between the overexpressed IQGAP1 and active Rac1 in CGN c.3560C > T mutant cancer cells." (PMID 38424547, 2024). "This study indicates that NEK2 promotes the metastatic behaviors of cancer cells by activating RhoA and Rac1 by phosphorylating RhoGDI1." (PMID 39768163, 2024). "For example, ITGB6 has been shown to promote cancer cell invasion by activating Rac1 signaling and promoting the formation of cellular protrusions and cell movement." (PMID 38344200, 2024). "The current research on the roles of RAC1 and RAC1B in therapy resistance in a variety of cancers suggests that research into the relationship between RAC1, RAC1B, and cetuximab resistance in CRC should be investigated." (PMID 39001533, 2024). "ΔNp63α indirectly controls PREX1 promoter transcriptional activity and downregulates its expression, which in turn inhibits activation of Rac1 and reduces cancer cell invasion." (PMID 38191532, 2024). "Our study suggests that EGFR and DOCK4-mediated RAC1 activation in response to secreted brain endothelial factors oppose this contractile phenotype, allowing cancer cells to cross the endothelium and propel themselves into the brain parenchyma." (PMID 38762624, 2024). "RAC1, in turn, induced radioresistance of cancer cells by promoting EMT through regulating the PAK1-LIMK1-Cofilins signaling." (PMID 38662050, 2024). "In the current study, the association of CGN c.3560 C > T with overexpressed IQGAP1 and Rac1 activation, promoting EMT, suggests a positive correlation between IQGAP1 and Rac1 in CGN c.3560 C > T-mutant cancer cells." (PMID 38424547, 2024). "Mechanistically, DAB2IP interacts with RAC1 and impedes RAC1-mediated β-catenin nuclear translocation, so that DAB2IP loss promotes the induction of cancer stem cell phenotypes and DOC resistance." (PMID 38902547, 2024). "Abnormal RAC1 activity contributes to irregular cell movement, making it a significant molecule in cancer research." (PMID 38577601, 2024). "In summary, our study identified a novel mechanism by which ΔNp63α inhibits Rac1 activity and cancer cell invasion." (PMID 38191532, 2024). "RAC1 is considered a potential target for combating cancer and various diseases like inflammation, metabolism, and neurodegeneration." (PMID 38378644, 2024). "Activated forms of RAC1 influence the overall survival and drug resistance in different types of cancer, and RAC1 expression levels have been proposed as a prognostic biomarker for patient survival." (PMID 40396280, 2024).